PACSIN2 (protein kinase C and casein kinase substrate in neurons 2)
Description:
Regulates the morphogenesis and endocytosis of caveolae (By similarity). Lipid-binding protein that is able to promote the tubulation of the phosphatidic acid-containing membranes it preferentially binds. Plays a role in intracellular vesicle-mediated transport. Involved in the endocytosis of cell-surface receptors like the EGF receptor, contributing to its internalization in the absence of EGF stimulus. Essential for endothelial organization in sprouting angiogenesis, modulates CDH5-based junctions. Facilitates endothelial front-rear polarity during migration by recruiting EHD4 and MICALL1 to asymmetric adherens junctions between leader and follower cells (By similarity). (Microbial infection) Specifically enhances the efficiency of HIV-1 virion spread by cell-to-cell transfer. Also promotes the protrusion engulfment during cell-to-cell spread of bacterial pathogens like Listeria monocytogenes. Involved in lipid droplet formation, which is important for HCV virion assembly.
Synonyms: SdpII
Tractability: Antibody: its Gene Ontology location is reachable by antibodies, with high confidence; UniProt places it where antibodies can reach, with medium confidence. PROTAC: ubiquitination databases record sites on it; its protein half-life has been measured.
Safety:
Unwanted effects reported when the protein is acted on. In parentheses: how it was acted on, where the effect was seen, and who reports it.
adverse events (source: ClinPGx)
GI toxicity (source: ClinPGx)
Gene: Protein-coding gene on chromosome 22 (42,835,412 to 43,015,185, reverse strand). Ensembl gene ENSG00000100266.
Subcellular location: Cytoplasm; Cytoplasm, cytoskeleton; Cytoplasmic vesicle membrane; Cell projection, ruffle membrane; Early endosome; Recycling endosome membrane; Cell membrane; Cell projection; Membrane, caveola; Cell junction, adherens junction
Subcellular location (Human Protein Atlas): Nuclear speckles; Plasma membrane; Centriolar satellite; Primary cilium; Vesicles
Pathways (Reactome):
Vesicle-mediated transport: Clathrin-mediated endocytosis
Gene Ontology:
Molecular function: cadherin binding; identical protein binding; phosphatidic acid binding; protein binding; phospholipid binding; protein-macromolecule adaptor activity; cytoskeletal protein binding; lipid binding
Biological process: caveola assembly; caveolin-mediated endocytosis; plasma membrane tubulation; protein localization to endosome; actin cytoskeleton organization; cell migration involved in sprouting angiogenesis; cell projection morphogenesis; cytoskeleton organization; regulation of endocytosis; modulation of chemical synaptic transmission
Cellular component: caveola; extracellular exosome; focal adhesion; plasma membrane; recycling endosome membrane; adherens junction; cytoplasm; cytoplasmic vesicle membrane; cytosol; early endosome; endosome; cell-cell junction; cytoskeleton; glutamatergic synapse; ruffle membrane
Genetic constraint (gnomAD): Loss-of-function variants: 24 observed, 64.4 expected, observed/expected ratio (o/e) 0.37, 90% interval 0.27 to 0.52. The upper end of that interval is the gene's LOEUF score, 0.52, which puts it in group 2 of 6, group 1 being the genes least tolerant of losing a copy. Missense variants: 503 observed, 653.83 expected, observed/expected ratio (o/e) 0.77, 90% interval 0.71 to 0.83. Synonymous variants: 245 observed, 260.08 expected, observed/expected ratio (o/e) 0.94, 90% interval 0.85 to 1.05.
Homologues: Orthologues: chimpanzee PACSIN2 (99% identical), dog PACSIN2 (94% identical), mouse Pacsin2 (94% identical), pig PACSIN2 (91% identical), rabbit PACSIN2 (91% identical), rat Pacsin2 (91% identical), guinea pig PACSIN2 (89% identical), tropical clawed frog pacsin2 (80% identical), zebrafish pacsin2 (64% identical), Drosophila melanogaster Synd (44% identical), Caenorhabditis elegans sdpn-1 (32% identical). Paralogues in human: PACSIN1 (62% identical), PACSIN3 (50% identical).
Diseases named in the same sentence as PACSIN2 in open-access papers:
PACSIN2 is named in the same sentence as 28 diseases in open-access papers, as found by Europe PMC text mining. Sharing a sentence is not in itself a finding about the gene and the disease. The quoted sentences say what the papers report.
leukemia (4 papers, 2019 to 2025). A malignant (clonal) hematologic disorder, involving hematopoietic stem cells and characterized by the presence of primitive or atypical myeloid or lymphoid cells in the bone marrow and the blood. "PACSIN2 polymorphism was shown to associate with TPMT activity, and knocking down PACSIN2 in a leukemia cell line reduced TPMT activity." (PMID 34990060, 2022). "In leukemia, the Cobbl1/SH3BP1/PACSIN2 axis promotes drug resistance and progression of chronic myeloid leukemia by regulating Rac1 activity, while the expression level of SH3BP1 is inversely correlated with the prognosis of acute myeloid leukemia." (PMID 40688112, 2025). "PACSIN2 moreover may affect TPMT activity: indeed, the knock-down of PACSIN2 mRNA in human leukemia cells NALM6 resulted in significantly lower TPMT expression and enzymatic activity that can in turn result in a higher tGTP availability and Rac-1 inhibition." (PMID 35582727, 2019).
acute lymphoblastic leukemia (3 papers, 2016 to 2022). Leukemia with an acute onset, characterized by the presence of lymphoblasts in the bone marrow and the peripheral blood. "PACSIN2 polymorphism was associated with thiopurine metabolism in children with acute lymphoblastic leukemia." (PMID 34168991, 2021). "Clinically, PACSIN2 polymorphism has been shown to be linked to drug‐induced hematological toxicity in patients with acute lymphoblastic leukemia (ALL) undergoing therapy." (PMID 35352878, 2022).
diabetes (2 papers, 2022 to 2023). "Interestingly, the association of PACSIN2 with nephrin is enhanced by either overexpression of rabenosyn‐5 or treating cultured podocytes with palmitate, the most abundant free‐fatty acid in humans and elevated in diabetes." (PMID 34990060, 2022). "Next, we explored whether the phosphorylation of PACSIN2 at S313 was an early feature of diabetes, preceding the onset of albuminuria." (PMID 37296607, 2023). "Our study shows that PACSIN2 is phosphorylated at S313 in diabetes and DKD." (PMID 37296607, 2023). "Given that PKCα activation is largely dependent on glucose concentrations in podocytes, it was surprising that PACSIN2 expression and phosphorylation at S313 did not associate with diabetes and hyperglycemia." (PMID 37296607, 2023). "For example, inducing diabetes in PACSIN2 knockout mice will reveal whether PACSIN2 is involved in the regulation of the renal function under diabetic conditions." (PMID 34990060, 2022). "Relying on a rat model for obesity, diabetes and severe DKD, along with human nephrectomy samples and serum samples from individuals with type 2 diabetes (T2D), we show that the phosphorylation of PACSIN2 at S313 associates with increased circulating free fatty acids (FFA) and kidney dysfunction." (PMID 37296607, 2023). "We hypothesized that diabetes and hyperglycemia alone were not sufficient to trigger the phosphorylation of PACSIN2." (PMID 37296607, 2023).
diabetic kidney disease (2 papers, 2020 to 2023). Progressive kidney disorder caused by vascular damage to the glomerular capillaries, in patients with diabetes mellitus. "PACSIN2 expression has been found to be upregulated in diabetic kidney disease." (PMID 32041280, 2020).
inflammatory bowel disease (2 papers, 2022 to 2023). A spectrum of small and large bowel inflammatory diseases of unknown etiology. "Higher autophagy and lower PACSIN2 levels were observed in inflamed compared with non-inflamed colon biopsies of inflammatory bowel disease pediatric patients at diagnosis." (PMID 36596605, 2023). "Moreover, the importance of PACSIN2 polymorphisms in the complications of thiopurine therapies may be context specific as it was shown that PACSIN2 polymorphism does not associate with the adverse effect of thiopurine when used for the treatment of inflammatory bowel disease." (PMID 34990060, 2022).
lung carcinoma (2 papers, 2021 to 2025). "Five of the eight NSCLC/lung cancers harboring a RASGRF fusion were adenocarcinomas (corresponding to the NSCLCs containing PACSIN2-RASGRF1, DLG1-RASGRF1, RP2-RASGRF1, NPTN-RASGRF1, and OCLN–RASGRF2)." (PMID 40615519, 2025). "The abundance of TLN1, TUBA4A, HSPA8, ITGB3, TSG101, and PACSIN2 in the plasma of lung cancer patients was measured using targeted mass spectrometry and compared to that in plasma from healthy volunteers." (PMID 34684727, 2021). "Together, these observations suggest that FN1, TLN1, ITGB3, HSPA8, and TUBA4A detection in the blood using SRM/SIS may serve as an indicator of tumors, and elevations in their concentrations coupled with PACSIN2 detection discriminate lung cancer from other malignancies." (PMID 34684727, 2021). "It is possible that a similar process occurs in lung cancer, also involving the EGFR binding partners EPS15 and PACSIN2." (PMID 34684727, 2021).
breast carcinoma (1 paper, 2021). "To further confirm the presence of IDR in the protein regions encoded by breast-cancer-associated AS events, we analyzed ADD3, PACSIN2, DIAPH1, MARK3, and MAP3K7 protein sequences with the PONDR web tool, a predictor of natural disordered regions." (PMID 34202984, 2021). "Finally, in our functional analysis of aberrantly expressed AS exons in breast cancer cells and tissues (PACSIN2 exon 8, DIAPH1 exon 2, MARK3 exon 16, ADD3 exon 13, and MAP3K7 exon 12), we found that dysregulated cassette exons encode for IDRs." (PMID 34202984, 2021). "Importantly, we were also able to confirm, by RT-PCR, the aberrant AS regulation of PACSIN2, DIAPH1, MARK3, ADD3, MAP3K7, and MARK2 in RNA extracts from two human tumor breast cancer samples tissues and two non-pathological tissues." (PMID 34202984, 2021).
cognitive decline (1 paper, 2024). "We showed that a subset of these proteins was associated with cognitive decline and levels of AD and neurodegeneration plasma biomarkers, including PIK3CG, PACSIN2 and PRKCB." (PMID 39143319, 2024).
glioma (1 paper, 2023). A benign or malignant brain and spinal cord tumor that arises from glial cells (astrocytes, oligodendrocytes, ependymal cells). "It has been reported to have a negative correlation with malignancy in glioma, whereas PACSIN2 was found to be downregulated in meningioma tumors when compared with controls in the meningioma datasets of BrainProt." (PMID 37887327, 2023).
Hyperglycemia (1 paper, 2023). An increased concentration of glucose in the blood. "This, however, matches the metabolic parameters of the ZDF rats at ages 8-weeks vs. 34-weeks (detailed in our previous study) showing that phosphorylation of PACSIN2 at S313 precedes hyperglycemia." (PMID 37296607, 2023).
tumor (3 papers, 2021 to 2022). "Our study found that PACSIN2 plays a negative regulatory role against Cobll1 as a potential tumor suppressor in CML." (PMID 35352878, 2022). "The newly identified role of PACSIN2 in sprouting angiogenesis also raises an interesting question whether PACSIN2 could be involved in tumour vessel generation by regulating this process." (PMID 34990060, 2022). "We confirmed an aberrant increase of cassette exon skipping in tumor specimens for PACSIN2 exon 8, DIAPH1 exon 2, FGFR1OP2 exon 4, MARK3 exon 16, DST exon 93, LMO7 exon 10, and RBM5 exon 7, whereas ADD3 exon 13, MAP3K7 exon 12, and MARK2 exon 15 were preferentially included in tumor specimens." (PMID 34202984, 2021). "However, we focused our attention on PACSIN2, DIAPH1, MARK3, ADD3, MAP3K7, and MARK2 cassette exons as these events were validated in both normal and cancer cell lines and in non-pathological and tumor breast specimens." (PMID 34202984, 2021).
cancer (2 papers, 2018 to 2021). A tumor composed of atypical neoplastic, often pleomorphic cells that invade other tissues. "Protein kinase C and PACSIN2 are reported to be involved in epithelial to mesenchymal transition of cancer stem-like cells, proliferation and survival of cancer stem-like cells and the aggressive nature of many cancers." (PMID 29298329, 2018).
kidney disease (1 paper, 2023). "Our experiments suggest that FFA accumulation triggers the phosphorylation of PACSIN2 at S313 via PKC and that pS313-PACSIN2 associates with the progression toward kidney disease." (PMID 37296607, 2023).
PACSIN2 also shares sentences with these, for which no sentence is quoted: adenocarcinoma (2 papers); chronic myeloid leukemia (2); acute myeloid leukemia (1); Alzheimer disease (1); amyloidosis (1); brain disorder (1); breast tumor (1); dementia (1); Hydrocephalus (1); infection (1); influenza (1); meningioma (1); osteosarcoma (1); schizophrenia (1); type 2 diabetes (1).